GAB2 (GRB2 associated binding protein 2)
Diseases named in the same sentence as GAB2 in open-access papers (continued):
Sharing a sentence is not in itself a finding about the gene and the disease.
soft tissue sarcoma (1 paper, 2021). A malignant neoplasm arising from muscle tissue, adipose tissue, blood vessels, fibrous tissue, or other supportive tissues excluding the bones. "Seven genes (LPP‐AS2, MUC1, GAB2, hsa‐let‐7i‐5p, hsa‐let‐7f‐5p, hsa‐miR‐101‐3p, andhsa‐miR‐1226‐3p) in a recurrent soft tissue sarcoma‐specific ceRNA network associated with recurrence and survival were identified based on the TCGA database." (PMID 34196116, 2021).
temporal lobe epilepsy (1 paper, 2024). A localization-related (focal) form of epilepsy characterized by recurrent seizures that arise from foci within the temporal lobe, most commonly from its mesial aspect. "Additionally, GAB2 has known associations with seizures, and is downregulated in rats with temporal lobe epilepsy." (PMID 39596674, 2024).
unipolar depression (1 paper, 2024). "RNA editing modifications were analyzed using a panel of eight genes (CAMK1D, GAB2, IFNAR1, KCNJ15, LYN, MDM2, PDE8A, PRKCB) that we previously identified and whose editing combinations were suggested as biomarkers to distinguish BD from unipolar depression and subcategories of BD patients." (PMID 39684694, 2024).
viral infection (1 paper, 2017). "To understand the possible role of GAB2 in CV-B3 infection, we first examined the protein level of GAB2 upon viral infection." (PMID 28361043, 2017). "Second, at the late stage of viral infection, cellular proteinases are activated, which further contributes to the reduced expression of GAB2 fragments." (PMID 28361043, 2017). "We next sought to determine the consequence of GAB2 cleavage during viral infection." (PMID 28361043, 2017). "Collectively, our results suggest that cleavage of GAB2 results in the loss of its function in promoting viral infection, rather than the gain of a pro-viral activity." (PMID 28361043, 2017).
tumor (47 papers, 2008 to 2026). "As a tumor suppressor, downregulated miR-197 targeted GAB2 (Grb2-associated binding protein), releasing the inhibited proliferation in tumor cells." (PMID 35606527, 2022). "Grb2-associated binders 2 (GAB2) contributed to tumor growth and angiogenesis through the upregulation of vascular endothelial growth factor expression, and it was also important in BRAF inhibition resistance." (PMID 34208938, 2021). "For instance, overexpression of Gab2 is suggested to be tightly associated with tumor proliferation and metastasis in BCa, melanoma and ovarian cancer." (PMID 30665442, 2019). "To explore the underlying mechanism of Gab2-mediated tumor cell growth and invasion, we determined the influence of the ERK, Akt, and Jak2 pathway inhibitors on the tumor-promoting activity of Gab2." (PMID 28842424, 2017). "In order to further clarify the underlying mechanism by which Gab2 promotes tumor growth and angiogenesis by the ERK pathway, we first looked at the expression of c-Myc, a versatile pro-oncogene in CRC." (PMID 28420432, 2017). "GAB2 phosphorylation of S505, S172, and T353 in normal tissue is higher than that in primary tumor tissue in UCEC." (PMID 38995439, 2024). "SNORA38B plays a role in promoting tumor progression in NSCLC by directly binding to E2F transcription factor (E2F1) and regulating the GAB2/AKT/mTOR pathway thereby contributing to the development of an immunosuppressive tumor microenvironment." (PMID 38406265, 2024). "We utilized the TIMER 2.0 online tool to explore the expression of GAB2 mRNA in tumor tissues and corresponding normal tissues in the TCGA database." (PMID 38995439, 2024). "There were differences in the expression of GAB2 phosphorylation in tumor tissues and corresponding normal tissues among different types of tumors." (PMID 38995439, 2024). "Many of these (DLK1, GAB2, BOLA2B, AOX1 and AGER) were closely related to cell proliferation and tumor progression, and associated with poor prognosis in HCC." (PMID 35331184, 2022). "We observed that NK92MI cells overexpressing Gab2 showed a stronger killing effect on tumor target cells compared to the control group at different effector-to-target ratios." (PMID 36248894, 2022). "In line with tumor growth, orthotopic tumors also showed higher expression of GAB2, PHOX2B genes than the subcutaneous tumor." (PMID 35197367, 2022). "Knockdown of GAB2 resulted in reduced cell proliferation, ascites induced cell migration, tumor growth, and formation of blood vessels." (PMID 33488950, 2020). "Although mechanistic target of MEK has an imperfect role in reducing Gab2-induced tumor growth and angiogenesis, in all, it works." (PMID 28420432, 2017). "In order to further clarify the mechanism by which Gab2 promotes tumor growth and angiogenesis, and upregulates the levels of VEGF in CRC, we first looked at the expression of c-Myc in different experiment groups." (PMID 28420432, 2017). "We found that overexpression of Gab2 in CRC cells induced tumor growth and angiogenesis through upregulating the levels of VEGF mediated by ERK/c-Myc pathway." (PMID 28420432, 2017). "The positive rates in tumor regions for GAB2, CRKL, and FRS2 were 40.00% (30/75), 53.95% (41/76), and 35.06% (27/77), respectively." (PMID 28558797, 2017). "Of note, Gab2 enhanced tumorigenesis and tumor growth in mouse xenografts with high Ki67 expression, and led to an increased vessel density with strong CD34 and VEGFR2 activity." (PMID 28420432, 2017). "On the basis of the tumor growth curve, overexpression of Gab2 in HepG2 cells markedly increased tumor growth, whereas the deletion of Gab2 in HepG2 cells clearly suppressed tumor development in nude mice." (PMID 28842424, 2017). "In the present study, we provided additional evidence showing the involvement of Gab2 in regulation of tumor angiogenesis." (PMID 28420432, 2017).
tumor (continued). "Overexpression of Gab2 in HCC cells promoted proliferation, migration, and xenograft tumor growth in nude mice, whereas Gab2 deficiency impaired these oncogenic effects in HepG2 cells." (PMID 28842424, 2017). "It has been reported that Gab2 expression is required for human tumorigenesis and tumor growth by increasing cell proliferation and independent growth." (PMID 28420432, 2017). "Meanwhile, we found that Gab2 overexpression in implanted tumor xenografs induced CRC cells proliferation and adjacent lymphatic invasion." (PMID 28420432, 2017). "Tumors in mice with Gab2-overexpressing cells were much larger compared with those in control mice, but tumor size was significantly diminished when Gab2 was knocked down in Gab2-overexpressing cells." (PMID 28842424, 2017). "We found that inducible suppression of GAB2 durably impaired tumor growth as the tumor burden signals remained low throughout the induction period." (PMID 26657155, 2016). "On the contrary, sar@LIP treatment induced slight up-regulation of GAB2, which supports its tumor stimulatory role." (PMID 27646588, 2016). "In this study, we show an important role of GAB2 overexpression in promoting tumor angiogenesis by upregulating expression of multiple chemokines." (PMID 26657155, 2016). "We confirmed that increased Gab2 expression correlated with higher tumor node metastasis stage and highly invasive CRC cell lines." (PMID 26754532, 2016). "Given the growing importance of Gab2 in several tumour entities we expect that our results will help to understand the complex regulation of Gab2 and how this docking protein can contribute to malignancy." (PMID 23607741, 2013). "Given the growing importance of Gab2 in several tumour entities, we expect that our approach and results will help to shed more light on the various mechanisms by which this docking protein contributes to malignancy." (PMID 23607741, 2013). "An early study demonstrated that in CD4-positive T cells derived from the rare human neoplasia mycosis fungoides, tyrosine-phosphorylated Gab2 interacted with SHP2 and STAT5a in a IL-2- regulated fashion." (PMID 19737390, 2009). "The levels of Gab2 protein are elevated in both c-ErbB2 tumours and bitransgenic tumours compared with normal gland controls, although the level is slightly higher in c-ErbB2 tumours than bitransgenic tumours." (PMID 18700973, 2008). "Our research findings suggest that GAB2 can serve as a potential tumor biomarker." (PMID 38995439, 2024). "It provides new possible ideas for studying the role of GAB2 in tumor occurrence and development." (PMID 38995439, 2024). "In addition, this study mainly compared the expression differences of GAB2 mRNA between tumor and corresponding normal tissue, and previous reports have mostly compared the expression differences of GAB2 at the protein level." (PMID 38995439, 2024). "Furthermore, we found 11 cancer-related gene sets from different tumor entities in the KEGG database downregulated in AML KO compared to AML WT mice, highlighting the strongly reduced disease aggressiveness in Gab2-deficient mice." (PMID 34903841, 2022). "Indeed, we found that when Gab2 is overexpressed in human NK cells, NK cell activity toward tumor cells significantly increases, indicating that Gab2 positively regulates the killing activity of human NK cells." (PMID 36248894, 2022). "MicroRNAs targeting Gab2 have been found in many tumors and inhibit tumor development." (PMID 36421826, 2022). "Thus, we believe that the importance of Gab2 in tumour progression should also be considered in future investigations." (PMID 33369107, 2021). "Furthermore, in addition to mediating these signalling pathways, Gab2 is also involved in cell migration and tumour progression." (PMID 33369107, 2021). "It has been reported that GAB2 promotes tumor cell metastasis, migration, and recurrence." (PMID 34568022, 2021). "Somatic amplification and overexpression of GAB2 have been noted in different tumor types." (PMID 33488950, 2020).
tumor (continued). "Besides Gab2, Gab1 is also shown to be positively correlated with tumor proliferation and metastasis in head and neck squamous cell carcinoma and colorectal cancer." (PMID 30665442, 2019). "To further confirm whether U0126 could inhibit Gab2-induced tumor growth and angiogenesis, we performed tumor xenograft model using BALB/C nude mice." (PMID 28420432, 2017). "Notably, overexpression of Gab2 in CRC cells induced tumor growth and angiogenesis in mouse xenografts through enhancing VEGF expression." (PMID 28420432, 2017). "Our results provided new evidence supporting the involvement of Gab2 in driving tumor angiogenesis." (PMID 28420432, 2017). "We then evaluated the tumorigenicity in DEN-evoked WT and Gab2-KO mice and found that there were many tumor nodules on the surface of livers from DEN-treated WT mice (upper right); however, there were significantly fewer and smaller tumors in livers from DEN-treated Gab2-KO mice (bottom right)." (PMID 28842424, 2017). "Furthermore, Gab2 knockout in HepG2 cells restrained cell proliferation, migration and tumor growth in nude mice." (PMID 28842424, 2017). "Furthermore, we found that suppression of GAB2 inhibited tumor cell proliferation and blood vessel formation as indicated by reduced Ki67 and CD31 staining, respectively, compared with tumors expressing the control shRNA." (PMID 26657155, 2016). "Next, we studied the effect of Gab2 on tumor metastasis in vivo." (PMID 26754532, 2016). "The amount of Tyr452-phosphorylated Gab2 is dramatically higher in the c-ErbB2 tumours compared with the bitransgenic tumours suggesting that expression of activated Akt1 in the bitransgenic animals attenuates phosphorylation of Gab2 and subsequent docking of PI3K, which occurs in c-ErbB2 animals." (PMID 18700973, 2008). "However, it is still unclear whether Docetaxel exerts anti-tumor effects by acting on GAB2, and further verification is needed." (PMID 38995439, 2024). "Thus, the role of GAB2 in tumor is related to its phosphorylation." (PMID 38995439, 2024). "Finally, we revealed that mechanistic target of mitogen-activated protein kinase (MEK) could attenuate Gab2-induced tumor growth and angiogenesis via altering VEGF and c-Myc levels." (PMID 28420432, 2017). "Studies to date demonstrate that Gab2 can promote the proliferation, growth factor autonomy, migration and invasion of cancer cells, indicating that it may contribute to several stages of tumour progression." (PMID 19737390, 2009). "The violin plots demonstrate that genes including CTNV, FIB, GAB2, LAMP3, ST3GAL1 and ST3GAL5 exhibit distinct expression profiles, with tumour tissues showing markedly different expression distributions compared to normal controls." (PMID 41362116, 2025). "Melanocytes were predominantly found in two tumor tissues, where CDK4 subpopulation was predominantly expressed in SM and GAB2 subpopulation was predominantly expressed in PM." (PMID 38528036, 2024). "Furthermore, three CML Supertarget genes, that is, GRB2-associated binding protein 2 (GAB2), son of sevenless homolog 1 (SOS1), and signal transducer and activator of transcription 5B (STAT5B), are the components of JAK/STAT signaling pathway critical in BCR-ABL1-positive neoplasms." (PMID 37297004, 2023). "GAB2 performs all these various oncogenic functions by mediating PI3K/AKT1/mTOR, MAPK, and IKKβ pathways in tumor cells that harbor GAB2 alteration." (PMID 33488950, 2020). "Overexpression of GAB2 in immortalized cells (HA1E-M and IOSE) induced tumor formation, but in FTSEC it increased the number of colonies." (PMID 33488950, 2020). "Expression levels of many proteins were altered with resistance development including gp100/PMEL, CD171/L1CAM, GAB2, mTOR and PI3K-p85 which have been previously shown to be upregulated in tumors including CMM and promoting tumor progression." (PMID 33082316, 2020).
tumor (continued). "Taken together, our results suggest that the activation of MEK/ERK/c-Myc pathway is required for Gab2-induced VEGF levels, tumor growth and angiogenesis." (PMID 28420432, 2017). "Tumor sequencing revealed LOH in CHEK2 and ATM, as well as CCND1 and GAB2 amplifications." (PMID 38091153, 2024). "Staining patterns of anti-GAB2 and anti-CRKL antibodies were both cytoplasmic and nuclear in the tumor regions, while that of the anti-FRS2 antibody was cytoplasmic and membranous in the tumor regions." (PMID 28558797, 2017). "Although mechanistic target of MEK only attenuates, not significantly suppresses Gab2-induced tumor angiogenesis, it works, in all." (PMID 28420432, 2017). "Then, we observed that MEK inhibitor could effectively inhibit Gab2-induced tumor growth with decreased tumor volume, growth rate and Ki67 expression, but not tumor weight." (PMID 28420432, 2017). "Finally, we evaluated the impact of Gab2 on the expression of c-Myc and VEGF, and the probable effect of mechanistic targeted extracellular signal-regulated kinase (ERK) pathway in suppressing tumor growth and angiogenesis." (PMID 28420432, 2017). "Interestingly, overexpression of Gab2 induces endothelial cell migration in response to VEGF, whereas its depletion using siRNAs results in its reduction, suggesting that Gab2 may play an important role in tumor angiogenesis." (PMID 28420432, 2017).
cancer (43 papers, 2012 to 2025). A tumor composed of atypical neoplastic, often pleomorphic cells that invade other tissues. "Additional cooperating mutations in known cancer genes (including Nf1, Ep300, Notch1, Sbds, and Ets1) were identified in 5 of the 9 GAB2 mAMLs." (PMID 40773291, 2025). "Because of its key role as scaffolding protein and in the binding with several transcription factors, Gab2 is implicated in several cancers of both solid and hematological origin." (PMID 32528972, 2020). "An impaired interaction between Gab2 and Grb2 is implicated in the onset and progression of different types of cancers, thus being a valuable potential anticancer drug target." (PMID 33171874, 2020). "through targeting specific genes such as MTA1 (metastasis-associated gene 1), Lin28B (Lin-28 homolog B) and Gab2 (Grb2-associated binding protein 2) in various cancers." (PMID 28881624, 2017). "Grb2-associated binder 2 (Gab2), a scaffolding adaptor protein, has recently been implicated in cancer progression." (PMID 26754532, 2016). "We also identified overexpression of scaffolding proteins that are traditionally involved in the AKT/mTOR pathway including IRS1, RICTOR, and GAB2, which have been implicated as oncogenic contributors in other cancer types." (PMID 25999352, 2015). "Gab2 knock out mice models, although displaying a deficient allergic response and mast cells developments, are viable and fertile and have proven to be a precious tool to pinpoint the role of this protein in cancer at a molecular level." (PMID 33171874, 2020). "The downregulation of miR-125b augments the expression of its target gene GRB2-associated-binding protein 2 (Gab2), thereby dramatically promoting cancer cell migration, which provides a novel epigenetic mechanism by which m6A modification on miRNAs promotes cancer metastasis." (PMID 29587823, 2018). "Gab2 is implicated in a number of cancers of both solid and haematological origin." (PMID 29137268, 2017). "Hence, it warrants further studies to determine if Akt inhibitors may effectively treat GAB2 mutant-associated hematological malignancies and GAB2-amplified cancers." (PMID 34419139, 2021). "The scatter plots reveal that ST3GAP1 and GAB2 exhibit highly significant differential expression patterns with false discovery rate (FDR) values reaching statistical thresholds across various cancer contexts." (PMID 41362116, 2025). "GAB2 has characteristics related to oncogenes and plays a significant role in the occurrence and development of various malignant tumors." (PMID 38995439, 2024). "In summary, the expression level of GAB2 mRNA has a significant impact on the prognosis of patients in various types of cancer." (PMID 38995439, 2024). "Second, there is a lack of additional clinical and experimental data to further validate the expression, function, and prognostic significance of GAB2 in pan-cancer." (PMID 38995439, 2024). "Based on TCGA and GTEx databases, we used TIMER2.0 online analysis tool and R language to analyze the expression of GAB2 in pan-cancer." (PMID 38995439, 2024). "We compared the core promoter-mutated genes with altered gene expression to the cancer driver gene list and observed that the somatic-mutated TERT and PRRX1, and germline-mutated GAB2 were on the list." (PMID 35033028, 2022). "The core promoter mutation in GAB2 and PRRX1 occurred at simple repetitive sequences, caused their altered expression in cancer." (PMID 35033028, 2022). "GAB2 is identified as an oncogene and binds to cell membrane receptors and downstream effectors to accelerate cell cancer." (PMID 34988109, 2021). "Our previous study suggests that miR‐125b mediates PAR2‐induced cancer cell migration by regulating Gab2 expression." (PMID 33369107, 2021). "Gab2 is a scaffolding protein, overexpressed in many types of cancers, that plays a key role in the formation of signaling complexes involved in cellular proliferation, migration, and differentiation." (PMID 33171874, 2020).